IL33 (interleukin 33)
Diseases named in the same sentence as IL33 in open-access papers (continued):
Sharing a sentence is not in itself a finding about the gene and the disease.
endometriosis (continued). "IL-33 treated mice with induced endometriosis are highly vascularized and exhibited increased proliferation." (PMID 33381124, 2020). "A critical regulator on chronic inflammation, serum IL-33, was abnormally elevated in women with endometriosis and principally in deeply infiltrating endometriosis." (PMID 33013364, 2020). "Previous reports showed that IL-33 was present in ascites of patients with endometriosis, and IL-33 concentrations were elevated in correlation with progression of the disease state, suggesting a relationship between IL-33 and the progression of endometriosis." (PMID 31507610, 2019). "The increased lesion volume and epithelial cell proliferation induced by rhIL-33 were completely suppressed by administration of anti-human IL-33 antibody, indicating that excessive levels of exogenous IL-33 exacerbated endometriosis in this mouse model." (PMID 31507610, 2019). "A previous report indicated that IL-33 levels were elevated in ascites from severe endometriosis patients." (PMID 31507610, 2019). "Here, we detected IL-33 only 4 h after transplantation, but we cannot exclude the possibility that low-level IL-33 is released continuously in the peritoneal cavity and contributes to the development of endometriosis." (PMID 31507610, 2019). "As uterine transplantation increased the concentration of IL-33 in the peritoneal cavity, we examined the influence of endogenous IL-33 on endometriosis-like lesion formation." (PMID 31507610, 2019). "Taken together, these findings reveal that IL-33 was produced intraperitoneally at the onset of endometriosis, thereby promoting cell proliferation and increasing the lesion." (PMID 31507610, 2019). "We investigated the role of IL-33, IL-1R1, and MyD88 in the development of endometriosis in mice, and demonstrated the potential of inhibitors for IL-1/IL-33 and their signaling pathway as therapeutic targets for endometriosis." (PMID 31507610, 2019). "Here, we examined the role of interleukin (IL)-1/IL-33 signaling in the development of endometriosis using a mouse model of endometriosis." (PMID 31507610, 2019). "In early studies, serum IL-33 was found to be abnormally elevated in women with endometriosis, particularly those with deeply infiltrating endometriosis (DIE)." (PMID 30205617, 2018). "To gain further insights into IL-33 signaling in the progression of endometriosis, we studied the effect of human rIL-33 stimulation of endometrial and endometriotic epithelial and endothelial cell lines." (PMID 29263351, 2017). "Together, our data generated from in vitro studies suggests that IL-33 promotes inflammation and angiogenesis, which likely impacts the inflammatory mileu and disease progression in endometriosis patients." (PMID 29263351, 2017). "Future studies are required to address the specific cell types in the endometriotic lesions as well as in the peritoneal cavity that are contributing to the elevated IL-33 levels in endometriosis patients." (PMID 29263351, 2017). "Collectively, we provide convincing evidence that IL-33 perpetuates inflammation, angiogenesis and lesion proliferation, which are critical events in the lesion survival and progression of endometriosis." (PMID 29263351, 2017). "In another study conducted in 30 endometriosis patients and 20 control women from Tunisia, IL-33 was reported to be higher in the serum and PF of women with endometriosis." (PMID 29263351, 2017). "Our patient data and in vitro data, along with previous reports, provide convincing evidence to suggest a potential role of IL-33 in endometriosis." (PMID 29263351, 2017). "Overall, the present study provides evidence to suggest that IL-33 is likely one of the important players contributing towards inflammation observed in advanced staged endometriosis patients and the progression of the disease." (PMID 29263351, 2017). "We investigated the role of IL-33 in the pathology of endometriosis using patient samples, cell lines and a syngeneic mouse model." (PMID 29263351, 2017).
endometriosis (continued). "Indeed, blocking IL‐33 or its receptor is a promising non‐hormonal therapy for endometriosis, and its efficacy is currently being tested in clinical trials." (PMID 40658772, 2025). "Additionally, another study reported elevated IL-33 levels in the peritoneal fluid of women with endometriosis, which correlated with the severity of the disease." (PMID 39767772, 2024). "Similarly, several human studies have revealed that IL-33 levels were elevated in plasma, serum, peritoneal fluid and endometriotic tissues of women with endometriosis compared with healthy controls." (PMID 39713054, 2024). "Numerous studies have shown increased concentrations of interleukins (IL-1, IL-6, IL-8, and IL-33), tumor necrosis factor-alpha, insulin-like growth factor 1, and vascular endothelial growth factor in endometriosis patients, among endometriosis lesions and peritoneal fluid." (PMID 39136014, 2024). "However, the the complete role of IL-33 in the development of endometriosis requires further exploration." (PMID 37816731, 2023). "Moreover, we conducted an experiment using endometriosis model mice that showed that a combination of IL-33-Ab and erastin treatment alleviated the disease, showing the promise of combining immunotherapy and ferroptosis therapy." (PMID 37816731, 2023). "In addition, we established a mouse model of endometriosis and employed a combination treatment involving IL-33 antibodies and a ferroptosis inhibitor, erastin." (PMID 37816731, 2023). "We thus postulate that macrophage-derived IL-33 may regulate eESCs survival, which ultimately advances the progression of endometriosis." (PMID 37816731, 2023). "IL-33 secreted from macrophages is known to accelerate the progression of endometriosis." (PMID 37816731, 2023). "Furthermore, the combined treatment of IL-33-Ab and erastin resulted in a reinforced therapeutic effect on endometriosis model mice." (PMID 37816731, 2023). "Thus, Tregs and endometriotic lesions engage active crosstalk through IL-33 to promote fibrogenesis in endometriosis, and, as such, this finding opens up new avenues to identify novel therapeutic targets for endometriosis." (PMID 36428461, 2022). "A previous study found that the IL33/ST2 pathway may participate in the pathogenesis of endometriosis and that IL33 serum cytokine levels in women with adenomyosis were decreased compared to those in controls." (PMID 35937844, 2022). "Mice intraperitoneally administered with an antibody against IL-33 developed limited endometriotic lesions, which indicates that IL-33 may be a novel therapeutic target for endometriosis." (PMID 36428461, 2022). "IL-33 observed in the peritoneal fluid was found to correlate with endometriosis severity." (PMID 36428461, 2022). "Thus, Tregs, which express ST2 in endometriotic lesions, are likely to be exposed to lesion-derived IL-33, which is consistent with the notion that this cytokine contributes to their differentiation into Th2-like cells in endometriosis." (PMID 36428461, 2022). "Thus far, we observed a consistent pathological effect of IL-33 in our murine model of endometriosis, and this pathological effect is dependent on ILC2s." (PMID 34699382, 2021). "While our studies were the first to our knowledge to reveal the molecular basis of how IL-33 in concert with ILC2s potentially drives endometriosis pathology, we acknowledge some of our study’s limitations, which are likely inherent to the field of endometriosis in general." (PMID 34699382, 2021). "Finally, we demonstrate the functionality of IL-33 neutralization as a promising and potentially novel therapeutic avenue for treating the debilitating symptoms of endometriosis." (PMID 34699382, 2021). "Importantly, we show that IL-33 drives hallmarks of severe endometriosis, including elevated inflammation, lesion proliferation, and fibrosis, and that this IL-33–induced aggravation is mediated by ILC2s." (PMID 34699382, 2021).
endometriosis (continued). "Our findings demonstrate the pathological role of IL-33–activated ILC2s in endometriosis, and we suggest that this axis could be a novel and promising nonhormonal therapeutic target for endometriosis." (PMID 34699382, 2021). "Furthermore, IL-33 contributed to the lesion survival and progression of endometriosis by perpetuating inflammation, angiogenesis, and lesion proliferation." (PMID 33013364, 2020). "Similarly, IL-33, which is in high concentration in endometriosis, can also induce a Th2 response on mast cells and Th2 cells." (PMID 33381124, 2020). "This inhibitor may provide a powerful therapeutic agent capable of suppressing the augmentation of endometriosis induced by IL-1β, IL-33, and LPS." (PMID 31507610, 2019). "We examined the effect of endogenous IL-33 on the onset of endometriosis." (PMID 31507610, 2019). "In the literature surrounding endometriosis and IL-33, there are only two reports so far." (PMID 29263351, 2017). "Therefore, it is possible that IL-33 plays a role in the progression of endometriosis; however, a significant knowledge gap exists with regards to how IL-33 contributes to the disease pathology and which tissues and cells are producing IL-33." (PMID 29263351, 2017). "Therefore, we used a syngeneic immunocompetent mouse model to understand the impact of an artificially elevated IL-33 microenvironment on the progression of endometriosis." (PMID 29263351, 2017). "Moreover, macrophage-derived IL-33/ST2 has been shown to inhibit ferroptosis in endometriosis through the ATF3/SLC7A11 axis, indicating that macrophages may influence endometriosis ferroptosis via SLC regulation." (PMID 41150779, 2025). "However, it is currently unclear whether IL-33 directly regulates ferroptosis to influence the disease course in endometriosis." (PMID 37816731, 2023). "Notably, the application of both IL-33-Ab and erastin slowed the development of endometriosis." (PMID 37816731, 2023). "Hence, we aimed to test whether ATF3 participates in the IL-33-mediated upregulation of SLC7A11 in endometriosis." (PMID 37816731, 2023). "Using endometriotic lesions obtained from patients with severe endometriosis (n = 3), dual staining for IL-33 with cytokeratin (epithelial cell marker) and vimentin (stromal cell marker) revealed that IL-33 colocalizes with both stromal and epithelial cells in the lesion microenvironment." (PMID 34699382, 2021). "Based on studies on peritoneal fluid, serum, or samples from endometriotic lesions in women, it has been suggested that IL33 might play an important role toward inflammation present in advanced-stage endometriosis patients and on the progression of the disease." (PMID 33134338, 2020). "Therefore, we first examined the effect of IL-33 on lesions in our mouse endometriosis model." (PMID 31507610, 2019). "However, IL-1α is also released from the nucleus when the cell is damaged (like IL-33), and we indeed detected IL-1α in the ascites at 8 hours after transplantation, thus IL-1α may also contribute to the development of endometriosis." (PMID 31507610, 2019). "Furthermore, by using rhIL-33 and anti-human IL-33 antibody, we demonstrated that neutralization of IL-33 was effective at inhibiting the progression of endometriosis, and the use of anti-human IL-33 antibody may provide a beneficial clinical treatment." (PMID 31507610, 2019). "Interestingly, IL-33 is a critical regulator of number of processes including inflammation, vascularization, hypernociception, and fibrosis, which are known to be involved in the pathophysiology of endometriosis." (PMID 29263351, 2017). "Increasing evidence suggests that interleukin-33 (IL-33) and TSLP levels are elevated in the peripheral blood, endometriotic endometrium, and peritoneal fluid of individuals with endometriosis." (PMID 39767772, 2024).
endometriosis (continued). "To explore the mechanism responsible for the IL-33/ST2-mediated activation of SLC7A11 in endometriosis, we first identified differentially expressed genes (DEGs) using an endometriosis dataset obtained from the GEO database (GSE19834)." (PMID 37816731, 2023). "This comparison revealed IL-33 and ATF3 as two significant regulators of ferroptosis in endometriosis." (PMID 37816731, 2023). "In the peritoneal fluid of a mouse endometriosis model, ILC2s were found to be the only ST2+ immune cell type that was increased in abundance in response to exogenous IL-33 treatment." (PMID 36428461, 2022). "In this study, we demonstrate, in both humans and a murine model, that IL-33 contributes to the expansion of group 2 innate lymphoid cells (ILC2s), and this IL-33–induced ILC2 expansion modulates the endometriosis lesion microenvironment." (PMID 34699382, 2021). "In this study, women with endometriosis demonstrated a hypercoagulable and inflammatory state, manifested by elevated levels of CRP, homocysteine, and fibrinogen as well as IL-17 and IL-33." (PMID 34754275, 2021). "Numerous researchers have found that factors such as IL-33, hypoxia, estrogen stimulation, and WNT4 may trigger EMT in endometriosis." (PMID 40757199, 2025). "Elevated IL‐33 and increased ILC2 correlate with worsening of the endometriotic lesions and fibrosis, suggesting that IL‐33 and ILC2 may be new targets for potential therapeutic intervention in endometriosis." (PMID 40658772, 2025). "In turn, high levels of IL-33 enhanced invasion ability of hOVEN-SCs via ST2/mitogen-activated protein kinase (MAPK)/matrix metalloproteinase MMP-9 signaling pathway, ultimately contributing to ovarian dysfunctions and endometriosis progression." (PMID 39713054, 2024). "This makes the IL-33/ST2 axis one of the most promising nonhormonal therapeutic targets for endometriosis." (PMID 34699382, 2021). "Therefore, using two separate methodologies, we show that IL-33–induced inflammation, immune cell recruitment, lesion proliferation, and fibrosis are indeed ILC2 dependent in the endometriosis murine model." (PMID 34699382, 2021). "Furthermore, we demonstrated that neutralizing antibodies to IL-33 and/or IL-1R1, or an inhibitor of IRAK4 (involved in MyD88 signaling) were effective for the treatment of endometriosis in this model." (PMID 31507610, 2019). "Previous reports indicated high levels of IL-33 in the serum and PF of deep infiltrating endometriosis patients, the source of IL-33 was not clear." (PMID 29263351, 2017). "Elevated serum but not peritoneal IL33 levels are correlated with the intensity of preoperative painful symptoms and with the extent and severity of the deeply infiltrating endometriosis." (PMID 23843796, 2013). "Our study, however, objectively provided evidence that IL-33 and ILC2s, including those not activated by IL-33, are of critical importance in the pathophysiology of endometriosis, which should be studied further, and that this axis is a promising, nonhormonal therapeutic target for the field." (PMID 34699382, 2021). "Therefore, IL-33 seems to be a promising, nonhormonal therapeutic target for treating endometriosis." (PMID 34699382, 2021). "In this study, we set out to understand whether endometriotic lesions from patients produce IL-33 and express its receptor ST2 and to understand the mechanistic basis of their involvement in the pathophysiology of endometriosis using representative cell lines and a syngeneic mouse model." (PMID 29263351, 2017). "However, the role of IL-33 in the progression of endometriosis is not well described." (PMID 29263351, 2017). "Additionally, we used the syngeneic immunocompetent mouse model of endometriosis, which may not truly represent the human condition, but it provided us with the opportunity to gain mechanistic insights on the disease progression in an artificially created IL-33 dominant microenvironment." (PMID 29263351, 2017).
hepatocellular carcinoma (31 papers, 2016 to 2025). A malignant tumor that arises from hepatocytes. "Interestingly, two different polymorphisms in the IL-33 gene have been reported to increase the expression of IL-33 and to be associated with higher risk to develop hepatocellular carcinoma." (PMID 34583655, 2021). "In a multivariable analysis, the infiltration of human hepatocellular carcinomas (HCC) by cells expressing IL-33 and by CD8+ T cells was associated with prolonged patient survival." (PMID 30416507, 2018). "IL‐33‐driven expansion of ILC2s also appears relevant for effective anti‐tumour responses in hepatocellular carcinoma (HCC), where patients with elevated IL‐33 levels and favourable ILC2 to ILC1 ratios exhibit improved clinical outcomes." (PMID 40899118, 2025). "In hepatocellular carcinoma cells, nuclear interleukin-33 (IL-33) SUMOylation stabilizes IRF1 to aid in immunological evasion." (PMID 38789431, 2024). "We also found that IL-33 expression in the hepatocellular carcinoma samples from patients with poor prognosis were lower than the samples from patients with better prognosis." (PMID 38097352, 2023). "Multifactorial Cox regression of 11 prognostic genes resulted in seven independent risk genes affecting the prognosis of patients with hepatocellular carcinoma, namely ENO1, NDRG1, NPM1, H2AX, IL33, MT3 and TXNRD1." (PMID 38097352, 2023). "Although there are good evidences showing that IL-33 can kill tumor in mice via NK cells, the role of IL-33 in hepatocellular carcinoma is still controversial depending on how IL-33 is applied." (PMID 32410845, 2020). "In this study, we examined the effect of exogenous IL-33 on the biological characteristics of hepatocellular carcinoma in humans and in mice." (PMID 33308251, 2020). "For example, decreased survival has been demonstrated in non-small cell lung cancer patients with high serum levels of IL-33 and in hepatocellular carcinoma patients with high serum levels of sST2." (PMID 30426271, 2018). "Of interest, in hepatocellular carcinoma resected tissues expression of IL-33 by intratumoral effector memory CD62L−KLRG1+CD107a+ CD8+ T cells was shown to be a prognostic marker for increased patients survival." (PMID 30483263, 2018). "Ectopic expression of IL-33 has been reported in hepatocellular carcinoma, and is related to tumor growth and metastasis." (PMID 27074834, 2016). "Recently, the fact that IL-33 could function as a senescent cell SASP was partially elaborated in a hepatocellular carcinoma model, which is consistent with our observations." (PMID 38369466, 2024). "However, the clinicopathological and prognostic significance of IL-33 in cancer patients, especially in patients with hepatocellular carcinoma (HCC), remains controversial." (PMID 37507682, 2023). "The first four markers’ expressions increased successively in the paracellular tissues, the hepatocellular carcinoma samples (from patients with better prognosis) and the hepatocellular carcinoma samples (from patients with poor prognosis), while IL-33 showed the opposite trend." (PMID 38097352, 2023). "In contrast, the expression of IL-33 was decreased in the hepatocellular carcinoma samples." (PMID 38097352, 2023). "In a mouse model for hepatocellular carcinoma, ectopic expression of IL-33 in tumor cells or hydrodynamical injection of IL-33–expressing plasmids into the liver of tumor-bearing mice inhibited tumor development by promoting effector CD4+ and CD8+ T cell activation and IFN-γ production." (PMID 34209038, 2021). "Serum levels of IL-33 are increased in breast, lung, gastric and hepatocellular carcinomas." (PMID 29587679, 2018). "Here, we examined the effect of exogenous IL-33 on the biological characteristics of hepatocellular carcinoma (HCC) and the possible mechanism of action." (PMID 33308251, 2020).